MIR4479 (microRNA 4479)
Synonyms: hsa-mir-4479
Gene: MicroRNA gene on chromosome 9 (136,886,733 to 136,886,803, forward strand). Ensembl gene ENSG00000266507.
Homologues: Orthologues: chimpanzee MIR4479 (100% identical).